FOS (Fos proto-oncogene, AP-1 transcription factor subunit)
Diseases named in the same sentence as FOS in open-access papers (continued):
Sharing a sentence is not in itself a finding about the gene and the disease.
osteosarcoma (continued). "Elevated expression of c-FOS was correlated with high-grade more frequently than with low-grade osteosarcoma." (PMID 19506729, 2008). "The c-FOS oncogene is overexpressed in a number of tumours including osteosarcoma breast carcinoma, cervical cancer, ovarian cancer and lung cancer." (PMID 19506729, 2008). "FOS can regulate prognostic genes related to osteosarcoma metastasis." (PMID 36772869, 2023). "MEF2C and FOS can regulate the prognostic genes related to Osteosarcoma Metastasis." (PMID 36408691, 2023). "In conclusion, immunohistochemistry against FOS/FOSB continues to represent the quickest, most cost-effective and reasonable diagnostic add-on to confirm the diagnosis of osteoblastoma and to exclude (osteoblastoma-like) osteosarcoma." (PMID 35347251, 2022). "Of note, the osteosarcoma sample showed multiple copies of the FOS-locus." (PMID 31768625, 2020). "Moreover, consistent with previous findings in which copy number gains were noticed in FOS immunopositive osteosarcoma, we also observed FOS positivity in two osteosarcoma samples (osteoblastic and sclerosing subtype)." (PMID 31768625, 2020). "Expression of c-FOS has been shown to be highly elevated in 60% of osteosarcoma samples." (PMID 19506729, 2008). "However, osteosarcomas with FOS expression have rarely been described." (PMID 40506925, 2025). "In the development of osteosarcoma, activated JNK protein, together with c‐Jun, c‐FOS, acts on core‐binding factor 1, leading to the transformation of osteoblasts into cancer cells." (PMID 38800967, 2024). "The identification of FOS/FOSB overexpression is helpful in routine diagnostics but as outlined is not present in all cases and can be identified also in a small subset of osteosarcomas." (PMID 35347251, 2022). "FOS rearrangements were absent in other bone-forming lesions with strong expression of FOS and for which we were able to perform FISH (osteosarcoma (n=1) and reactive bone with callus formation (n=1))." (PMID 31768625, 2020). "ERK/JNK and c‐JUN/c‐FOS, as upstream activators of FOXP1, drive osteosarcoma development." (PMID 36772869, 2023). "This suggests that the approach shown here can indeed help in discriminating osteoblastoma from conventional osteosarcoma even in the absence of a detectable FOS/FOSB fusion, representing a useful complementary tool." (PMID 35347251, 2022). "We then examined 55 whole-genome sequences of two published osteosarcoma series, none of which harboured break points in FOS or FOSB11,12." (PMID 29858576, 2018). "Indeed, osteosarcoma can infrequently show nuclear FOS expression and a small fraction of osteoblastomas seem to arise independent of FOS/FOSB rearrangements." (PMID 35347251, 2022). "Notably, five osteoblastoma-like osteosarcomas were immunohistochemically completely negative for FOS, the remaining case of which we included two manifestations was focally positive in one sample and negative in the other." (PMID 35347251, 2022). "Although numbers are small, our present results indicate that immunohistochemistry and/or FISH for FOS can be of help in distinguishing (epithelioid) osteoblastoma from osteosarcoma, especially since there are no specific antibodies or molecular tests for osteosarcoma." (PMID 31768625, 2020). "Unfortunately, even by reducing the number of tumor types evaluated, the described approach could not distinguish osteoblastoma-like osteosarcoma from osteoblastoma in 4/5 evaluable cases but 5/6 cases lacked FOS expression and the remaining tumor showed only focal positivity." (PMID 35347251, 2022).
depression (54 papers, 2009 to 2026). "FOS, a proto-oncogene, is widely expressed and implicated in AD, the mechanical and ischemic brain injuries, epilepsy and depression." (PMID 39469068, 2024). "Within the AP-1 transcription factor family (including FOS, JUN, JUNB, and JUND), FOS expression is markedly reduced in stress-induced depressive mouse models, correlating with depression-like behaviors under chronic social defeat stress (CSDS)." (PMID 41479556, 2026). "The five hub genes, RNF24, MGAM, FOS, and TKT, were deemed potential diagnostic and prognostic markers for patients with pain–depression comorbidity." (PMID 39125922, 2024). "Another study reported that rice wine can potentially reduce stress-induced depression-like behaviors and FOS expression in rats." (PMID 38297317, 2024). "The second module targets FOS for depression treatment through the DRD1/5-GNAQ-PLC B1-DAG-PRKCA cascade signal." (PMID 38628641, 2024). "As a result, we discovered 43 key genes associated with pain–depression comorbidity, along with the identification of RNF24, MGAM, FOS, TKT, and SIGLEC5 as hub genes." (PMID 39125922, 2024). "The second module control downstream FOS to treat depression by targeting the DRD1/DRD5--GNAQ--PLCB1--DAG--PRKCA cascade reaction." (PMID 34867413, 2021). "The second module is target to the DRD1/5-GNAQ-PLC B1-DAG-PRKCA cascade signal to control the downstream FOS to treat depression." (PMID 34867413, 2021). "These pathways are linked to the core genes chiefly including FOS, IL6, TNF-α, Bcl-2, c-Jun, ERK, and EGF gene in our research in the treatment of depression." (PMID 32997725, 2020). "Notably, this is the first data demonstrating the mRNA levels of PPAR-γ, FOS, and JUN and their association with clinical response in depression population." (PMID 41479556, 2026). "Many studies have reported altered expression of FOS in models of depression." (PMID 38297317, 2024). "Our data suggest that PPT may achieve the treatment of depression by inhibiting the expression of FOS, enhancing the expression of TTR and KL, and modulating the PI3K-AKT signaling pathway." (PMID 39062817, 2024). "In this module, ADCYAP1R1, PRKACA, MAPK8, MAPK14, GRIA1, and FOS are both targeted genes of CGFC and pathogenic genes of depression; RHOA is a specific targeted gene of CGFC, and most of these genes are related to the pathogenesis or treatment of depression." (PMID 34867413, 2021). "Intersecting 87 targets predicted by network pharmacology for PPT for depression with 350 DEGs from transcriptome sequencing yielded a total of three target genes (TTR, FOS, and KL)." (PMID 39062817, 2024). "Some of the common down genes in maternal C57 mice and depression were for the MAP kinase pathway and some of the common down genes included: FOS, EGR1, DUSP1, BDNF, NR4A1, NR3C1, the neuropeptide somatostatin (SST), and one of the its receptors, SSTR2." (PMID 34997033, 2022). "Notable downregulated genes matching depression were: BDNF, the glucocorticoid receptor, NR3C1, and activity related genes, EGR1, FOS, NR4A1, FOSB, and ARC." (PMID 34997033, 2022). "These genes included SBNO2, CEACAM5, AKAP1, UBC, ACTB, UBB, and FOS for schizophrenia; SEC24C, PGLYRP1, ARHGAP4, RPL22, SLC6A11, and SYK for bipolar disorder; and SRRT, PARK2, LILRA4, STK17A, IGFBP2, and NF1 for major depression." (PMID 22373040, 2011). "We concluded that PPT might be therapeutic in depression through the PI3K-AKT signaling pathway and unearthed three key targets (TTR, FOS, and KL)." (PMID 39062817, 2024).
COVID-19 (46 papers, 2020 to 2025). A disease caused by infection with severe acute respiratory syndrome coronavirus 2. "Although the pathogenic mechanism of FOS in COVID-19 is unknown, it has been proposed as a therapeutic target." (PMID 39469068, 2024). "ADRB2, FOS, and IL-6 were found to be associated with COVID-19 inflammation." (PMID 35127768, 2021). "The COVID-19 high-stage-specific markers (i.e., FOS, CXCL8, HLAA, JAK3, ICAM1, and H2BC4) were overexpressed in higher-stage samples, that is, increased expression levels of the markers were observed in asymptomatic to critical samples." (PMID 41155463, 2025). "High FOS expression is a key feature of COVID-19 patients, making it a potentially promising target for managing SARS-CoV-2 infection." (PMID 41155463, 2025). "Conversely, FOS, which was low in healthy and moderate patients, showed a dramatic increase in severe COVID-19 cases, indicating heightened inflammation and ineffective interferon antiviral responses." (PMID 39928675, 2025). "Specifically, the IRF7 (+) regulon was activated in severe COVID-19, whereas FOS (+) and JUNB (+) regulons were activated in healthy neutrophils." (PMID 38612651, 2024). "The proteins encoded by the ‘dark’ genes TRADD, FOS and DDGs RELB, JUN, IKBKG are involved in the MAPK signaling pathway, which is a potential signaling pathway for the spread and development of COVID-19." (PMID 37853311, 2023). "Recent studies have identified FOS as a potential drug target for COVID-19 patients through a bioinformatics approach." (PMID 36249762, 2022). "We screened a total of 112 compounds and found that CHEMBL348436 (also known as Cirsimaritin) has the potential to regulate blood leukocyte pyroptosis in COVID-19 patients while simultaneously improving prognosis through FOS and NFKB1A inhibition." (PMID 35928821, 2022). "Classical monocytes in the patient with acute stage of BNT162b2-myocarditis were similar to those in the patients with COVID-19 in terms of decreased level of JUN/FOS expression and increased regulon activity of CEBPB." (PMID 36225942, 2022). "FOS gene expression was reported to be increased in total monocytes in people with COVID-19 compared to healthy controls, similar to our results." (PMID 34108966, 2021). "Moreover, both KLF2 and FOS were downregulated in myeloid cells coming from individuals with severe Delta COVID-19." (PMID 39712003, 2024). "In addition to the potential targets like the MAPK-14 inhibitors and FOS, we conducted the protein-drug interaction analysis of the shared DEGs between COVID-19 and the neurological diseases, identifying the candidate COVID-19 therapies." (PMID 39469068, 2024). "In addition, FOS was found to have potential as a new target for puerarin in the treatment of COVID-19." (PMID 37468850, 2023). "In fact, drugs targeting FOS have therapeutic effects in COVID-19 patients." (PMID 35928821, 2022). "We hypothesize that RELA, JUN, NF-κB1, NF-κB2, and FOS are the main targets of puerarin in the therapy of EHF/COVID-19 based on protein interactions." (PMID 35663983, 2022). "Cytokine storms caused by COVID-19 can be prevented by reducing JUN and FOS expression." (PMID 36380355, 2022). "The computed data suggested that these MPO and FOS genes may be potential drug targets of luteolin action in treating PC and COVID-19." (PMID 35178029, 2021). "Given that IFI27 was significantly increased in all patients with COVID-19 and FOS was dramatically decreased in recovered patients, these two markers might be used for disease condition prediction in the future." (PMID 33677468, 2021). "This suggests that FOS is a candidate marker for COVID-19 patient recovery." (PMID 33677468, 2021). "However, except for FOS, ephedrine regulates 19 other genes; thus, more extensive studies are needed to elucidate the role of FOS and the effect of ephedrine on the treatment of COVID-19 patients." (PMID 35458567, 2022).
COVID-19 (continued). "Interestingly, the gene encoding FOS was downregulated in the SEV group at endpoint B compared to controls at endpoint A (contrast 4), indicating that B12, in addition to blocking the binding of this TF to the regulatory region of CCL3, also reduces its expression in severe COVID-19." (PMID 36993968, 2023). "Mapping relation examination between COVID-19 and Ephedra-Glycyrrhiza exhibited that the key markers were tumor necrosis factor-α (TNF-α), interleukin-2 (IL-2), albumin (ALB), FOS proto-oncogene, and prostaglandin- endoperoxide synthase 2 (PTGS2)." (PMID 37654998, 2023). "Early studies have confirmed that JUN, FOS, and ATF3 are up-regulated in COVID-19 patients and correlated with the severity of COVID-19." (PMID 36380355, 2022). "Similarly, other genes involved in type I interferon signaling (IFITM1 and IFITM3) and cellular activation (UBC, FOS, and DUSP1) were increased in a severity-dependent manner, suggesting an enhanced EF B-cell activity associated with an overt inflammatory condition in severe COVID-19." (PMID 35899045, 2022). "We identified FOS, NFKB1, JUNB, JUN, and NFKB1A as core target genes of quercetin for the treatment of COAD/COVID-19." (PMID 36249762, 2022). "Here, we reported the mRNA upregulation of STAT3 together with its well-known downstream effectors c-FOS and c-JUN in COVID-19 patients compared with healthy controls." (PMID 35327634, 2022). "By constructing a protein-protein interaction (PPI) network, we ascertained FOS, NFKB1, NFKB1A, JUNB, and JUN as possible core target genes of quercetin for the treatment of COAD/COVID-19." (PMID 36249762, 2022). "We screened the genes based on their degree values and identified RELA, BCL2, JUN, FOS, and MAPK1 as possible core target genes for puerarin in treatment of COVID-19/COAD." (PMID 35677450, 2022). "From 11 healthy cell-type TRNs and 8 COVID-19 cell-type TRNs, we identified 8 unique central TFs, FOXP1, RUNX1, FOS, SMAD3, JUN, NFKB1, PPARG, and STAT3." (PMID 35458567, 2022). "IL6, CXCL8, EGFR, FOS, PIK3R1, and NFKB1 were identified as common targets from the common pathways between cancers and COVID-19 (signaling by interleukins, TLR signaling, TNF-α signaling via NF-kB)." (PMID 34067609, 2021). "Pathway analysis between Ephedra-Glycyrrhiza and COVID-19 showed that the key targets were TNF-α, IL2, FOS, ALB, and PTGS2." (PMID 33581688, 2021). "Collectively, these results suggest that suppressing high severity-specific markers (i.e., FOS, CXCL8, and HLA-A) may help prevent COVID-19 progression." (PMID 41155463, 2025). "Based on our results, we suggest that controlling high-severity-specific markers (FOS, CXCL8, HLA-A, JAK3, ICAM1, and H2BC4) and low-severity-specific markers (IL1B, CD3D, CD4, CCL5, and SNRPB) may prevent COVID-19 progression." (PMID 41155463, 2025). "Moreover, we identified that more than half of the Mon IFI30 marker peaks were shared with monocytes from infants affected with COVID-19, and BACH1, NFE2L2, FOS, and FOSL2 are the master regulators of the cell state." (PMID 39712003, 2024). "In addition, we found that some TFs were differentially expressed in severe COVID-19, including TF upregulations of IRF7, SP100, HMGB2, and BCL6, and downregulations of FOS and JUNB." (PMID 38612651, 2024). "Similarly, for CD14 and CD16 monocyte cells in severe COVID-19, CEBPD and FOS were particularly activated in the two cell types, and CEBPD upregulated S100A8 and S100A9." (PMID 37936693, 2023). "Similarly, SPDEF and ELF3 were found to be activated in squamous cells, and CEBPD and FOS were shared between CD14 and CD14 monocytes in severe COVID-19." (PMID 37936693, 2023). "The two TFs were RUNX1 in the TRNs of healthy B cells, basophil/mast cells, dendritic cells, macrophage/monocyte cells, NK cells and COVID-19 patients’ AT2 cells and B cells and FOS in the TRNs of healthy ciliated and endothelial cells and COVID-19 patients’ ciliated cells and NK cells." (PMID 35458567, 2022).
COVID-19 (continued). "In this study, through network pharmacology, molecular docking, target analysis, and tissue analysis, it can be concluded that Xiyanping injection and andrographolide sulfonates such as compound III in the treatment of COVID-19 mainly act on HSP90AA1, CAT, TNF, FOS, and other targets." (PMID 35818408, 2022). "Moreover, motif footprint analysis revealed increased accessibility of genomic regions containing FOS and JUN motifs in COVID-19 patients relative to healthy volunteers in myeloid cells, a signal which was also seen in convalescence." (PMID 35216673, 2022). "Importantly, above immune findings were used for a Bayesian network model, which significantly revealed FOS, CXCL8, IL1β, CST3, PSAP, CD45 and CD74 as COVID-19 severity predictors." (PMID 36532041, 2022). "Finally, using a Bayesian Network model, we identified FOS, CXCL8, IL1β, CST3, PSAP, CD45 and CD74 as predictors of the COVID-19 disease." (PMID 36532041, 2022). "By using Cytoscape software to visualize the degree of each gene in the PPI network, we found that RELA, BCL2, JUN, FOS, and MAPK1 had the highest degree, suggesting that the five genes might be core targets of puerarin in COVID-19/COAD comorbidity." (PMID 35677450, 2022). "Consistent with our scRNA-seq data, the expression profile of FOS, which is a transcription factor mediating the MAPK pathway, showed significant upregulation in patients with COVID-19 but obvious downregulation in recovered patients by real-time RT-PCR analysis." (PMID 33677468, 2021). "Taken together, luteolin-mediated anti-PC and COVID-19 benefits could be accomplished through regulation of core gene activities, especially MPO and FOS." (PMID 35178029, 2021). "FOS, JUN, NFKB1, JUNB, and NFKB1A had the highest degree values, so we concluded that these genes might be the core target genes of quercetin for the treatment of COAD/COVID-19." (PMID 36249762, 2022). "Notably, the mitogen-activated protein kinase (MAPK) pathway (i.e., FOS, JUN, JUNB, and DUSP1) was greatly suppressed in all recovered patients compared with that in the HCs, which suggested that inhibition of the MAPK signaling pathway is a recovery sign of COVID-19 patient." (PMID 37853311, 2023).